SNORA15B-1 (small nucleolar RNA, H/ACA box 15B-1)
Gene: Small nucleolar RNA gene on chromosome 7 (65,070,538 to 65,070,672, forward strand). Ensembl gene ENSG00000207062.
Gene Ontology:
Biological process: RNA processing
Cellular component: nucleolus
Homologues: Orthologues: mouse Snora15 (83% identical), rat LOC120096108 (81% identical). Paralogues in human: SNORA15B-2 (100% identical), SNORA15 (97% identical).